BCL3 (BCL3 transcription coactivator)
Diseases named in the same sentence as BCL3 in open-access papers (continued):
Sharing a sentence is not in itself a finding about the gene and the disease.
autoimmune disease (6 papers, 2013 to 2024). A disorder resulting from loss of function or tissue destruction of an organ or multiple organs, arising from humoral or cellular immune responses of the individual to their own tissue constituents. "Bcl‐3 dysregulation has been observed in several autoimmune diseases, and Bcl3‐deficient animals are more susceptible to bacterial and parasitic infections." (PMID 39046369, 2024). "This study provides novel insights and targets to further explore the specific mechanisms by which Bcl-3 regulates the mTOR pathway, maintains immune homeostasis, and prevents inflammation and autoimmune diseases by targeting Bcl-3 molecules." (PMID 37794349, 2023). "In the development of autoimmune diseases, Bcl-3 has also been shown to play an anti-inflammatory role." (PMID 35355979, 2022). "In humans, Bcl-3 is also related to the occurrence and development of many diseases and malignant tumors, such as various inflammatory and autoimmune diseases, blood tumors and solid tumors." (PMID 35355979, 2022). "In terms of autoimmune diseases it should be noted, that BCL-3 is also a suppressor of autoimmune diabetes, as BCL-3-deficient NOD mice are more susceptible to autoimmune diabetes and display higher levels of IL-17." (PMID 23578005, 2013). "Altered Bcl-3 expression levels have been observed in several autoimmune diseases." (PMID 27023613, 2016). "Importantly, a more in depth understanding of the roles played by Bcl-3 in immune pathologies could, in time, encourage the therapeutic targeting of this important regulator of NF-κB as a way of controlling autoimmune disease and other immunopathologies." (PMID 27023613, 2016).
breast tumour (6 papers, 2010 to 2024). "In contrast to the modest effects of BCL3 on breast tumour growth kinetics, spontaneous metastasis of BCL3-null tumours was found to be dramatically reduced compared to their BCL3 controls." (PMID 38195591, 2024). "It is possible that Bcl3, one of the main partners of p52, over expressed in human clinical breast tumour specimens, interacts with p52 to form an oncogenic DNA-binding complex p52/p52/Bcl3 and play a role in breast tumourigenesis." (PMID 24281078, 2010). "Furthermore, it was also shown that MCPIP1 functions as a potent tumor suppressor and induces apoptosis of breast tumor cells by selectively enhancing mRNA decay of antiapoptotic gene transcripts, including Bcl2L1, Bcl2A1, RelB, Birc3, and Bcl3." (PMID 28197812, 2017).
diabetes (5 papers, 2016 to 2022). "Susceptibility to diabetes is also affected by c-Rel-deficiency in mice, which confers resistance to low-dose streptozotocin-induced diabetes, indicating that Bcl-3 may be influencing diabetes susceptibility through its role in the classical pathway of NF-κB activation." (PMID 27023613, 2016). "Among the common genes of depression and diabetes, there are four TFs, namely, BCL3, MXI1, GMEB2, NFKB1." (PMID 34833079, 2021). "This work also identified Bcl-3 as a regulator of chemokine gene expression in diabetes, and suggested a possible role for Bcl-3 in TH17 cell expansion and/or survival through an IL-23-dependent mechanism." (PMID 27023613, 2016). "Furthermore, even though a few other CpGs were found to be associated with alcohol consumption, diabetes or cancer, such as cg18181703 in SOCS3 and cg26470501 in BCL3, most of them also showed associations with smoking exposure in our analyses." (PMID 28303888, 2017). "In the absence of Bcl-3, the plasticity of TH1 cells is increased, allowing for an enhanced conversion to TH17 cells in response to IL-23, and it is possible that such alterations in the properties of diabetogenic T cells aid the development of diabetes." (PMID 27023613, 2016).
multiple myeloma (5 papers, 2009 to 2024). "This work shows for the first time that myeloma cells from MM patients express BCL3 and that high expression of BCL3 at the time of diagnosis is associated with reduced survival." (PMID 19191868, 2009). "We have not shown that BCL3 is an independent adverse prognostic factor and the exact relevance of elevated expression of BCL3 in myeloma high-risk disease is currently unclear." (PMID 19191868, 2009). "Importantly, and in concordance with the patient data, we found that the induction of Bcl-3 by cytokines was associated with increased proliferation of myeloma cells." (PMID 19191868, 2009). "BCL3 is a common target gene for several growth-promoting cytokines in myeloma cells and high expression of BCL3 at the time of diagnosis is associated with poor prognosis of patients with multiple myeloma (MM)." (PMID 19191868, 2009). "It has been shown before that IL6 is capable of inducing BCL3 transcription in multiple myeloma cells via STAT3 binding to an enhancer in the BCL3 gene body." (PMID 34422669, 2021). "Our results indicate a potential role for Bcl-3 in the development of multiple myeloma, and further studies are needed to clarify this." (PMID 19191868, 2009). "We propose that Bcl-3 contributes to regulation of NFκB-dependent gene transcription in myeloma cells, with potential oncogenic consequences." (PMID 19191868, 2009). "Bcl-3 was induced in myeloma cell lines by interleukin (IL)-6, IL-21, IL-15, tumor necrosis factor-α and IGF-1, and its upregulation was associated with increased proliferation of the cells." (PMID 19191868, 2009). "Our data showed that stimulation of myeloma cells with various cytokines well-known to promote proliferation increased Bcl-3 expression." (PMID 19191868, 2009). "We here present evidence that BCL3 is overexpressed in myeloma cells from a subset of myeloma patients, and that the high expression of BCL3 at the time of diagnosis is associated with inferior prognosis." (PMID 19191868, 2009). "The starting point of this study was our observation that IL-6, IL-21 and TNF-α induced expression of BCL3 in the myeloma cell lines OH-2 and IH-1." (PMID 19191868, 2009). "Based on this we decided to study the role of BCL3 in primary myeloma cells as well as in myeloma cell lines in more detail." (PMID 19191868, 2009). "As growth-promoting cytokines are frequently present in the bone marrow of MM patients, cytokine signaling is a highly possible mechanism for upregulation of Bcl-3 in myeloma cells in vivo." (PMID 19191868, 2009). "Gene expression of BCL3 was studied in 351 newly diagnosed myeloma patients, 12 patients with smouldering myeloma, 44 patients with monoclonal gammopathy of undetermined significance and 22 healthy individuals." (PMID 19191868, 2009). "Bcl3 expression was induced by IL-6 in multiple myeloma cells, which increased apoptosis." (PMID 35327480, 2022). "Cytokines that induced Bcl-3 also induced proliferation of the corresponding myeloma cell line." (PMID 19191868, 2009). "We wanted to study if Bcl-3 is a nuclear protein in myeloma cells." (PMID 19191868, 2009). "Microarray experiments done in our laboratory showed that the myeloma cell growth factors interleukin (IL)-6, IL-21 and tumor necrosis factor (TNF)-α all induced expression of the putative oncogene BCL3 in the myeloma cell lines IH-1 and OH-2 (paper in preparation)." (PMID 19191868, 2009). "It is therefore tempting to speculate that the nuclear presence of Bcl-3 as after IL-6 stimulation activates a different set of genes than activation of the classical and/or alternative NFκB pathway in myeloma cells." (PMID 19191868, 2009). "Furthermore, high expression of Bcl-3 in myeloma cell lines induced by growth-promoting cytokines is associated with increased proliferation of the cells." (PMID 19191868, 2009).
multiple myeloma (continued). "Meanwhile, overexpression of Bcl-3 increased cell apoptosis, although Bcl-3-specific siRNA did not affect the viability of a multiple myeloma (mm) cell line (ina-6)." (PMID 35355979, 2022). "When looking at the Bcl-3 protein expression in CD138+ plasma cells from eight myeloma patients, we detected Bcl-3 in seven of eight samples with Western blot (data not shown)." (PMID 19191868, 2009). "However, the expression of BCL3 in myeloma patient samples has not been studied." (PMID 19191868, 2009).
Obesity (5 papers, 2017 to 2023). Accumulation of substantial excess body fat. "Research suggests that Bcl-3 may be a potential new modulator of lipid metabolism in the development of obesity by establishing an obese mouse model under a high-fat diet." (PMID 37794349, 2023). "The latest evidence suggests that Bcl-3 may serve as a novel metabolic modulator that governs lipid metabolism in obesity." (PMID 37794349, 2023). "Recent studies suggest that Bcl-3 may be a new metabolic regulation factor that regulates lipid metabolism during the development of obesity." (PMID 35355979, 2022). "Surprisingly, we did not detect any major effect of injury and obesity on the expression levels of TNF or the associated genes Bcl3, Errfi1, Irak3, Myd88, and Thbs1 in our obese model." (PMID 29922174, 2018). "Therefore, the obesity model of Bcl-3-/-mice was established by a high-fat diet for 16 weeks." (PMID 35355979, 2022). "Moreover, Bcl-3 can regulate lipid metabolism in the occurrence and development of obesity, which implies that the regulation of Bcl-3 on inflammation and immune cells may be related to metabolism and indicates an emerging mechanism by which Bcl-3 regulates cell function through metabolism." (PMID 35355979, 2022).
Alzheimer disease (4 papers, 2017 to 2025). A progressive, neurodegenerative disease characterized by loss of function and death of nerve cells in several areas of the brain leading to loss of cognitive function such as memory and language. "Age-related up-regulation of Bcl3, as shown here, was also observed in brains suffering from mild cognitive impairment and Alzheimer’s disease." (PMID 36497123, 2022). "The mutations in BCL3 have been associated with HDL-C level, fasting insulin level and Alzheimer's disease (AD)." (PMID 33499918, 2021). "The BCL3, CFLAR, SMAD1, and HIF1A genes have been identified to be associated with late-onset Alzheimer's disease." (PMID 28558704, 2017).
anaplastic large cell lymphoma (4 papers, 2009 to 2024). Anaplastic large cell lymphoma (ALCL) is a rare and aggressive peripheral T-cell non-Hodgkin lymphoma, belonging to the group of CD30-positive lymphoproliferative disorders, which affects lymph nodes and extranodal sites. "The Bcl3 gene is a proto-oncogene candidate, currently considered to be a molecular marker of anaplastic large cell lymphoma and over-expression of the Bcl2l14 gene has been shown to induce apoptosis in cells." (PMID 22558084, 2012). "Additional potential mechanisms for upregulation of Bcl-3 in MM patients are gains/amplification of the BCL3 gene, as described in patients with anaplastic large cell lymphoma, or translocations involving chromosome 19, as found in patients with CLL." (PMID 19191868, 2009). "Notably, classical Hodgkin/Reed-Sternberg (HRS), anaplastic large cell lymphoma (ALCL) and T cell lymphomas, exhibit constitutive p50 homodimer activity associated with Bcl-3, verified by EMSA and IP shift." (PMID 30205516, 2018). "BCL3 is an established oncogene in hematologic malignancies, having been originally identified at a recurring translocation site in patients with B-cell chronic lymphoma and subsequently identified to be elevated in patients with anaplastic large cell lymphoma." (PMID 38195591, 2024).
colorectal tumours (4 papers, 2016 to 2022). "We propose that patients with higher BCL-3 expressing colorectal tumours have poorer survival at least in part because it promotes increased HR activity, allowing cells to tolerate and repair DNA damage caused by therapeutic agents." (PMID 35468497, 2022). "Immunochemistry analyses revealed significantly higher Bcl-3 and Ac-K49-β-catenin protein levels in colorectal tumors than in normal colons." (PMID 32355204, 2020). "Here we investigate the role of nuclear factor-κB (NF-κB) co-factor B-cell CLL/lymphoma 3 (BCL-3) in promoting colorectal tumour cell survival." (PMID 26033966, 2016). "Taken together, the data demonstrates that BCL-3 expression increases colorectal tumour cell survival through suppressing apoptosis." (PMID 26033966, 2016). "Similar results were obtained for the adenoma-derived cell line RG/C2, confirming that BCL-3 acts as a potent survival factor through activation of the AKT/PKB signalling pathway in colorectal tumour cells." (PMID 26033966, 2016). "Targeting BCL-3 may be an effective mechanism to prevent the reversion of LGR5+ cells in colorectal tumours." (PMID 30792270, 2019). "By suppressing BCL-3, it is tempting to speculate that this might reduce the Wnt signalling level to below the ‘just right’ threshold in colorectal tumour cells, preventing deregulated transcription of select Wnt target genes." (PMID 30792270, 2019). "Subsequently, both Bcl-3 and CD133 mRNA levels were found to be significantly increased in human colorectal tumors compared with their paired normal biopsies." (PMID 32355204, 2020). "Further, despite the fact that we could not show consistent regulation of c-MYC protein levels by BCL-3 in any of the cell lines (data not shown) the two studies describe potentially complementary mechanisms that clearly emphasise the importance of BCL-3 expression in colorectal tumour cell growth." (PMID 26033966, 2016).
COVID-19 (4 papers, 2020 to 2025). A disease caused by infection with severe acute respiratory syndrome coronavirus 2. "Finally, according to the GO Cellular Component analysis of 30 vessels of severe COVID-19-associated cancer, it was determined that the I-kappaB/NF-kappaB complex, Bcl3/NF-kappaB2 complex, and Bcl2 family protein complexes in the nucleus were enriched." (PMID 41472277, 2025). "Concordantly, for downstream genes of AP-1, the expression levels of some chemokine genes (e.g., CCL2, CXCL1, CXCL2, and CXCL10) were downregulated, while the expression levels of immune negative regulation genes (e.g. BCL3, NFKBIA, SOCS3, and TNFAIP3) were upregulated during the COVID-19 recovery." (PMID 33361761, 2020).
glioblastoma (4 papers, 2020 to 2024). The most malignant astrocytic tumor (WHO grade IV). "BCL3 was previously found to be a putative proto-oncogene in human cancers and attenuates the efficacy of temozolomide in glioblastoma cells." (PMID 35488886, 2022). "BCL3 regulation of STAT3 expression has been described in cervical, and glioblastoma cell lines, where shRNA knockdown of BCL3 resulted in decreased STAT3 and in the latter, pSTAT3 protein levels, while overexpression of BCL3 promoted the increase in STAT3 protein levels in both cell types." (PMID 38195591, 2024).
inflammatory bowel disease (4 papers, 2015 to 2022). A spectrum of small and large bowel inflammatory diseases of unknown etiology. "The observation that Bcl-3 KO increases the severity of inflammation has been corroborated in an inflammatory bowel disease model (Crohn’s disease and ulcerative colitis)." (PMID 31930327, 2020). "Here we show that Bcl-3 expression levels in colonic T cells correlate with disease manifestation in patients with inflammatory bowel disease." (PMID 28452361, 2017). "BCL-3 is upregulated in tissue from patients with inflammatory bowel disease, although further data from inflammatory bowel disease patients have shown that CpG sites in the BCL3 gene are commonly methylated and therefore repressed in B cells isolated from diseased tissue." (PMID 31930327, 2020). "Thus, we clarify that overexpression of Bcl-3 affects T-cell function, whereas Bcl-3 deficiency acts by enhancing epithelial cell survival, targeting the activity of Bcl-3 in inflammatory bowel disease may be a valid tactic to inhibit intestinal inflammation." (PMID 35355979, 2022). "Furthermore, Bcl-3 expression in the colon of inflammatory bowel disease (IBD) patients was significantly increased compared to healthy individuals." (PMID 25929479, 2015).
liver cancer (4 papers, 2017 to 2024). An epithelial or non-epithelial malignant neoplasm that arises from the liver. "The role of Bcl3 in regulating senescence in cancer is not well understood, with only one study on liver cancer demonstrating a role for Bcl3 in regulating SASP factors." (PMID 38255248, 2024). "We used diethylnitrosamine (DEN) combined with carbon tetrachloride (CCl4) (DEN-CCl4) to establish liver cancer model in wild-type (WT) mice and Bcl3 knockout (Bcl3−/−) mice." (PMID 34530917, 2021). "However, it has been reported that overexpressed Bcl3 is closely correlated with a poor prognosis for liver cancer." (PMID 35351855, 2022). "To explore the mechanistic role of Bcl-3 during hepatocarcinogenesis, we used the two-stage diethylnitrosamine (DEN)/phenobarbital (PB) model of liver cancer in transgenic mice exhibiting a hepatocyte-specific overexpression of Bcl-3 (Bcl-3Hep) and corresponding littermate wild type controls." (PMID 28915576, 2017).
lung carcinoma (4 papers, 2017 to 2022). "The fold changes in gene expression in lung cancer relative to asthmatic cell lines were in line with the in silico prediction for the genes BCL3, CD44, PPARD, POSTN, FOSB, and STAT1." (PMID 35406434, 2022). "Analysis of the enriched genes derived from the pathway analysis identified seven genes expressed in both the asthma and lung cancer sets: BCL3, POSTN, PPARD, STAT1, MYC, CD44, and FOSB." (PMID 35406434, 2022). "Analysis of the enriched genes derived from the pathway analysis identified seven genes present in both asthma and lung cancer: BCL3, POSTN, PPARD, STAT1, MYC, CD44, and FOSB." (PMID 35406434, 2022). "They reported an increase in BCL3 expression in lung cancer." (PMID 33765916, 2021). "The fold change in expression showed significant upregulation for the genes BCL3, CD44, PPARD, POSTN, and STAT1 in lung cancer patients compared to asthmatics." (PMID 35406434, 2022). "In particular, the genes BCL3, CD44, PPARD, and STAT1 showed an increase in expression among the mixed group (asthmatics diagnosed with lung cancer) and lung cancer samples." (PMID 35406434, 2022). "However, the results from this study warrant further investigation into the molecular mechanisms of the four genes (PPARD, STAT1, BCL3, and POSTN) in both asthma and lung cancer cell lines, independently and in combination." (PMID 35406434, 2022). "Similarly, BCL3, CD44, PPARD, and STAT1 were upregulated in both the mixed group and lung cancer samples; thus, they may also be involved in the transition." (PMID 35406434, 2022). "In our analysis, based on the expression of BCL3 and EGFR in response to L4.5 sub-lineage when compared to L3-CAS1 sub-lineage, we hypothesize that infection by the L4.5 sub-lineage strain may be potent to deteriorate lung carcinoma by promoting tumor growth and angiogenesis." (PMID 33765916, 2021).
nasopharyngeal carcinoma (4 papers, 2007 to 2024). A carcinoma arising from the nasopharyngeal epithelium. "Bcl-3 is also overexpressed and activated in nasopharyngeal carcinomas, where it is bound to p50 homodimers." (PMID 22195643, 2011). "Many cell growth and survival promoters can induce Bcl-3 expression, and Bcl-3 overexpression has been detected in other cancers such as nasopharyngeal carcinoma (NPC)." (PMID 17626640, 2007). "BCL3 is overexpressed in breast cancers, subtypes of lymphomas and nasopharyngeal carcinomas." (PMID 19191868, 2009). "Bcl-3 as an oncoprotein is overexpressed in nasopharyngeal carcinoma (NPC)." (PMID 17626640, 2007).